DMD (dystrophin)
Diseases named in the same sentence as DMD in open-access papers (continued):
Sharing a sentence is not in itself a finding about the gene and the disease.
Duchenne muscular dystrophy (continued). "Duchenne muscular dystrophy (DMD) is a severe X‐linked recessive disorder caused by pathogenic variants in the dystrophin gene, resulting in complete or partial absence of the dystrophin protein." (PMID 40254293, 2025). "A drastic reduction in DG in muscle tissue, caused by an absence of dystrophin, leads to muscle cell death and the symptomatology of Duchenne muscular dystrophy, which is caused by a mutation in the X-linked dystrophin gene." (PMID 40141196, 2025). "Background and aims: Duchenne muscular dystrophy (DMD) is a progressive neuromuscular disorder caused by mutations in the dystrophin gene, resulting in a complete absence of the dystrophin protein." (PMID 40542581, 2025). "Duchenne muscular dystrophy (DMD) is an X-linked recessive neuromuscular disease caused by mutations in the DMD gene, which encodes dystrophin—a protein that acts as a mechanical link between the cytoskeleton and the extracellular matrix, safeguarding muscle cells from contraction-induced damage." (PMID 39939773, 2025). "Duchenne muscular dystrophy (DMD) is caused by DMD mutations leading to absent or severely deficient levels of dystrophin protein." (PMID 40084496, 2025). "When the AAV vector that carried IscB.m16*-CBE targeting the dystrophin gene was injected into a Duchenne muscular dystrophy mice model, there was a G-to-H (H = A, T, or C) conversion with an efficiency of 7%, along with a 40% increase in the dystrophin protein levels." (PMID 40076976, 2025). "Duchenne muscular dystrophy (DMD) is a genetic disorder caused by almost total lack of the muscle dystrophin protein and characterized by progressive muscle weakness and wasting." (PMID 38265797, 2024). "Duchenne muscular dystrophy (DMD) is a severe X-linked recessive disorder arising from mutations in the dystrophin gene that result in a complete absence of dystrophin protein expression." (PMID 38339125, 2024). "Duchenne muscular dystrophy (DMD) is an X-linked, rare neuromuscular disease that is characterized by progressive muscle weakness and is caused by mutations in the DMD gene, which encodes the dystrophin protein." (PMID 38753764, 2024). "Duchenne muscular dystrophy (DMD) is a progressive neuromuscular disease caused by mutations to the dystrophin gene, resulting in deficiency of dystrophin protein, loss of myofiber integrity in skeletal and cardiac muscle, and eventual cell death and replacement with fibrotic tissue." (PMID 39056750, 2024). "Duchenne muscular dystrophy (DMD) is a rare genetic disorder caused by the absence of a fully functional dystrophin protein in myocytes." (PMID 39595988, 2024). "Such mutations can lead to a complete absence of dystrophin (Duchenne muscular dystrophy; DMD) or a truncated transcript (Becker muscular dystrophy; BMD)." (PMID 39061981, 2024). "Dystrophin is a low abundant cytoskeletal protein located in the membrane of the muscle fibre, and it is routinely analysed by IHC or Western blot for the diagnosis of Duchenne muscular dystrophy (DMD) and Becker muscular dystrophy (BMD) which are caused by a decrease or absence of the protein." (PMID 37801117, 2024). "Duchenne muscular dystrophy (DMD) is an X-linked genetic disorder resulting from mutations in the DMD gene, leading to the absence of dystrophin in the muscle membrane." (PMID 38702481, 2024). "An emblematic example is represented by the cognitive deficits in Duchenne muscular dystrophy, where dystrophin is well-known to be involved in brain metabolism, although the mechanisms underlying its role in neuronal plasticity have still only been partially investigated." (PMID 39451985, 2024). "Duchenne muscular dystrophy (DMD) is a progressive neuromuscular disease (NMD) caused by a dystrophin gene mutation that results in a lack of the dystrophin protein." (PMID 38344392, 2024).
Duchenne muscular dystrophy (continued). "Duchenne Muscular Dystrophy (DMD) is a X-linked genetic disease characterised by muscle weakness and progressive degeneration due to a mutation found on the DMD gene that encodes for the DYSTROPHIN protein." (PMID 38585275, 2024). "Duchenne muscular dystrophy (DMD) is a genetic disease produced by variants in the DMD gene leading to a reduced expression or absence of the subsarcolemmal protein, dystrophin." (PMID 39045456, 2024). "We previously developed MYOD1-transduced UDCs (MYOD1-UDCs) as a model recapitulating the pathogenesis of Duchenne muscular dystrophy (DMD) caused by a lack of dystrophin." (PMID 38282008, 2024). "For example, Duchenne muscular dystrophy (DMD) shows genetic heterogeneity, with around 80% of patients having exon deletions or duplications in the dystrophin gene, and about 20% presenting with sequence variants, including intronic mutations in 5%, which complicates diagnosis." (PMID 39593150, 2024). "The lack of functional dystrophin protein in Duchenne muscular dystrophy (DMD) causes chronic skeletal muscle inflammation and degeneration." (PMID 37980539, 2023). "Our prior work from Finding the Optimal Regimen for Duchenne Muscular Dystrophy (FOR‐DMD) study showed that 38% of the enrolled boys reported speech delay, and this symptom was more common in boys with distal DMD mutations compared to those with proximal DMD mutations." (PMID 37804000, 2023). "Duchenne muscular dystrophy (DMD) is a fatal muscle disorder caused by a lack of dystrophin, resulting in loss of muscle mass and function, respiratory and cardiac failure, and premature death." (PMID 36831159, 2023). "Duchenne muscular dystrophy is a lethal muscle wasting disease caused by the absence of the protein dystrophin." (PMID 36587764, 2023). "Duchenne muscular dystrophy (DMD) is caused by the lack of dystrophin, a cytoskeletal protein essential for the preservation of the structural integrity of the muscle cell membrane." (PMID 37208786, 2023). "Duchenne Muscular Dystrophy (DMD) is caused by mutations in the dystrophin gene that cause an almost complete lack of the dystrophin protein in the patient." (PMID 36979809, 2023). "The lack of the protein DYSTROPHIN caused by mutations in the dystrophin gene results in Duchenne muscular dystrophy (DMD), a genetic disorder that affects the cardiac and skeletal muscle system." (PMID 36979114, 2023). "Eteplirsen, an antisense-oligonucleotide drug for skipping exon 51 from the Dystrophin gene, is available on the market, which may help up to 14% of Duchenne muscular dystrophy patients." (PMID 37759719, 2023). "To gain insight on dystrophin (DMD) gene transcription dynamics and spatial localization, we assayed the DMD mRNA amount and defined its compartmentalization in myoblasts, myotubes, and skeletal muscle biopsies of Duchenne muscular dystrophy (DMD) patients." (PMID 37743371, 2023). "Here, we studied the brain distribution and exon-skipping efficacy of two ASO chemistries, PMO and tcDNA, when delivered to the cerebrospinal fluid (CSF) of mice carrying a deletion in exon 52 of the dystrophin gene, a model of Duchenne muscular dystrophy (DMD)." (PMID 36980249, 2023). "To date, four PMO drugs have been approved by the FDA: eteplirsen, golodirsen, viltolarsen, and casimersen (Eteplirsen targets exon 51, Golodirsen and Viltolarsen target exon 53, and Casimersen targets exon 45 of the dystrophin mRNA) for Duchenne Muscular Dystrophy." (PMID 37830609, 2023). "Both spontaneous and bioengineered mouse models that lack the dystrophin protein isoform Dp427-M have been instrumental in the detailed elucidation of the molecular and cellular pathogenesis of Duchenne muscular dystrophy, as well as the evaluation of experimental treatment strategies." (PMID 37509144, 2023). "Lack of dystrophin expression is the underlying genetic basis for Duchenne muscular dystrophy (DMD)." (PMID 37402716, 2023).
Duchenne muscular dystrophy (continued). "Duchenne muscular dystrophy (DMD) is a severe inherited dystrophy of childhood, affecting 1 in 5,000 live male births due to X-linked mutations in the dystrophin gene that prevent the expression of functional dystrophin at the sarcolemma of individual muscle fibers." (PMID 37122711, 2023). "Duchenne muscular dystrophy (DMD) is a severe and common form of muscular dystrophy, with an estimated incidence of about 1 in 3800 male births, and is caused by diverse inherited and spontaneous mutations in the X‐linked dystrophin gene." (PMID 37311604, 2023). "When dystrophin is nonfunctional or absent in humans, skeletal muscle suffers from a severe pathology that causes Duchenne muscular dystrophy (DMD)." (PMID 36651896, 2023). "Despite the full cloning of the Dystrophin cDNA 35 years ago, no effective treatment exists for the Duchenne Muscular Dystrophy (DMD) patients who have a mutation in this gene." (PMID 36979809, 2023). "Duchenne muscular dystrophy (DMD, MIM #310200) is the most frequent inherited muscle disorder caused by truncating mutations, mainly frameshift deletions or nonsense variants, in the huge DMD gene located on Xp21.2-p21.1 (MIM *300377)." (PMID 37686372, 2023). "Duchenne muscular dystrophy (DMD) is an X-linked genetic disease resulting in muscle degeneration owing to the absence of the protein dystrophin in affected males; it also leads to dystrophic cardiomyopathy, which is a major cause of patient mortality." (PMID 36919695, 2023). "Duchenne muscular dystrophy (DMD) is a lethal muscle disease caused by absence of the protein dystrophin, which acts as a structural link between the basal lamina and contractile machinery to stabilize muscle membranes in response to mechanical stress." (PMID 36995778, 2023). "The mdx mouse model of Duchenne muscular dystrophy (DMD), a progressive muscle degeneration most commonly caused by dystrophin gene frameshift mutations, is characterised by a single point mutation in exon 23 of the dystrophin gene, resulting in the deficiency of dystrophin expression in muscle." (PMID 36965009, 2023). "Moreover, AS-circRNAs with adeno-associated virus (AAV) delivery corrected the open reading frame and restored the dystrophin expression in a mouse model of Duchenne muscular dystrophy." (PMID 37040525, 2023). "Duchenne muscular dystrophy (DMD) is a muscle disease characterized by the absence of the protein dystrophin, which causes a loss of sarcolemma integrity, determining recurrent muscle injuries, decrease in muscle function, and progressive degeneration." (PMID 35562874, 2022). "The most frequently inherited disorder of the neuromuscular system is Duchenne muscular dystrophy, which is characterised by primary abnormalities in the X‐chromosomal DMD gene resulting in the almost complete loss of the dystrophin isoform Dp427‐M in skeletal muscle tissues." (PMID 35902360, 2022). "We used it to insert specific point mutations in exons 9, 20, 35, 43, 55 and 61 of the Duchenne Muscular Dystrophy (DMD) gene coding for the dystrophin protein, which is absent in DMD patients." (PMID 35682838, 2022). "The lack of dystrophin in cardiomyocytes in Duchenne muscular dystrophy (DMD) is associated with progressive decline in cardiac function eventually leading to death by 20–40 years of age." (PMID 35681116, 2022). "Duchenne muscular dystrophy is an X-linked genetic disease which results from mutations in the DMD gene leading to a lack of dystrophin expression in muscle fibres." (PMID 35682838, 2022). "Duchenne muscular dystrophy (DMD) is caused by out-of-frame mutations in the DMD gene resulting in the absence of a functional dystrophin protein, leading to a devastating and progressive lethal muscle-wasting disease." (PMID 36388984, 2022).
Duchenne muscular dystrophy (continued). "For example, in Duchenne Muscular Dystrophy (DMD), a hereditary muscle wasting disorder driven primarily by loss of the protein dystrophin, researchers have utilized ASOs to partially restore protein expression of dystrophin." (PMID 35295579, 2022). "We also explored relationship between CUB and mutations in the muscle dystrophin (DMD) gene, the larger X-linked human gene, which mutations do cause Duchenne muscular dystrophy and highlighted that its 2828 pathogenic variations occurred non-randomly in codons." (PMID 35358230, 2022). "For example, eteplirsen is an FDA-approved translation-blocking morpholino ASO used in Duchenne muscular dystrophy (DMD) to induce skipping of the mutated exon in dystrophin, which allows the translation of an almost full-length functional form of the protein encoded by the DMD gene." (PMID 35214734, 2022). "Furthermore, it has been shown that ADSCs have a high regenerative capacity in vivo as they can be incorporated into muscle fibers after ischemia and can significantly restore dystrophin expression in mdx mice, an animal model for Duchenne muscular dystrophy." (PMID 36550950, 2022). "Duchenne Muscular Dystrophy is a severe, genetic disease, caused by the lack of functional dystrophin in the affected muscles." (PMID 35590083, 2022). "Duchenne muscular dystrophy is a severe neuromuscular disease causing a progressive muscle wasting due to mutations in the DMD gene that lead to the absence of dystrophin protein." (PMID 35690627, 2022). "The mdx mouse exhibits repeated bouts of muscle degeneration and regeneration across its lifespan, but unexpectedly, the model does not mimic the severity of the human condition of Duchenne’s muscular dystrophy despite the same loss of the dystrophin protein." (PMID 36267576, 2022). "The aim of this study was to establish the possible effect of age, corticosteroid treatment and brain dystrophin involvement on motor function in young boys affected by Duchenne Muscular Dystrophy who were assessed using the North Star Ambulatory Assessment between the age of 4 and 7 years." (PMID 35905042, 2022). "Duchenne muscular dystrophy (DMD, OMIM #310200), an X-linked recessive disorder, characterized by progressive muscle degeneration and weakness, is caused by variations in the DMD gene (OMIM #300377), including deletions (60%–70%), duplications (10%), small rearrangements, and point mutations." (PMID 35615378, 2022). "Duchenne muscular dystrophy is a severe debilitating genetic disease caused by different mutations in the DMD gene leading to the absence of dystrophin protein under the sarcolemma." (PMID 36320324, 2022). "Finally, the large size of the mutated genes such as dystrophin (14 kb mRNA) in Duchenne Muscular Dystrophy (DMD) or dysferlin (6.2 kb mRNA) in limb–girdle muscular dystrophy type 2B (LGMD2B) and Miyoshi myopathy, challenges classical gene replacement therapies." (PMID 35910413, 2022). "Duchenne muscular dystrophy (DMD) is a lethal X-linked recessive genetic disease, characterized by mutations of the dystrophin gene leading to fibrosis, inflammation and progressive weakness and degeneration of cardiac, respiratory and skeletal muscles resulting in premature death of DMD patients." (PMID 35978142, 2022). "Moreover, they showed that transcriptional induction of utrophin, a protein product which is very similar to dystrophin, improved muscle strength in a mouse model of Duchenne muscular dystrophy (DMD) by local application of the AAV-gRNAs." (PMID 35097003, 2021). "Duchenne muscular dystrophy is a fatal muscle degenerative disease caused by the absence of a functional dystrophin protein." (PMID 34305644, 2021).
Duchenne muscular dystrophy (continued). "DMD mutations inducing Duchenne muscular dystrophy (DMD) seemed particularly well suited, since internal truncations of the protein may lead to a shortened but stable protein with partial functional restitution and a milder disease progression, as seen in the allelic Becker muscular dystrophy (BMD)." (PMID 33531685, 2021). "Duchenne muscular dystrophy (DMD) is a lethal pediatric muscle disorder caused by a mutation in the region Xp 21.2 (dystrophin gene) that leads to an absence of dystrophin protein." (PMID 33574358, 2021). "This hypothesis is similar to that proposed for Duchenne muscular dystrophy (DMD), where the loss of dystrophin increases the fragility of the muscle cell membrane, making them susceptible to tension-stress forces during muscle contraction and results in muscle cell rupture and death." (PMID 34354059, 2021). "Duchenne muscular dystrophy (DMD), an X-linked, recessive, fatal, muscle-wasting disease that affects approximately 1 in 5000 boys is caused by null mutations in the gene that encodes for dystrophin." (PMID 34384671, 2021). "As example, in 2008 Park and collaborators, established the first iPSCs line from skin fibroblasts from a patient affected by Duchenne muscular dystrophy (DMD), a fatal genetic disorder caused by mutations in the dystrophin (DMD) gene and characterized by progressive muscle wasting." (PMID 33937264, 2021). "Duchenne muscular dystrophy is caused by the absence of the protein dystrophin from skeletal muscle and is characterized by progressive cycles of necrosis/regeneration." (PMID 34950049, 2021). "ROS-activated cSrc tyrosine kinase (TK) promotes the degradation of β-dystroglycan (β-DG), a dystrophin-glycoprotein complex component, which may reinforce damaging signals in Duchenne muscular dystrophy (DMD)." (PMID 34827740, 2021). "Duchenne muscular dystrophy (DMD) is an X-linked progressive muscle-wasting disorder that is caused by a lack of functional dystrophin, a cytoplasmic protein necessary for the structural integrity of muscle." (PMID 33564172, 2021). "In Duchenne muscular dystrophy, the affected dystrophin complex interacts also with the sodium channel, which could also contribute to the difference in sodium imaging between normal-appearing muscles of a Duchenne patient and FSHD muscles." (PMID 33047224, 2021). "Duchenne muscular dystrophy (DMD) is an X-linked recessive progressive lethal disorder caused by the lack of dystrophin, which determines myofibers mechanical instability, oxidative stress, inflammation, and susceptibility to contraction-induced injuries." (PMID 33916762, 2021). "In this respect, we recently reported retinal neuron damage and synapse alterations in flies carrying full-length dystrophin defects, which paralleled well with the results obtained in mdx mice, the most commonly employed models in Duchenne muscular dystrophy research." (PMID 34439445, 2021). "Lack of dystrophin causes muscle degeneration, which is exacerbated by chronic inflammation and reduced regenerative capacity of muscle stem cells in Duchenne Muscular Dystrophy (DMD)." (PMID 34716330, 2021). "Duchenne muscular dystrophy (DMD) is a severe, progressive neuromuscular disorder caused by reading frame disrupting mutations in the DMD gene leading to absence of functional dystrophin." (PMID 33362201, 2020). "Duchenne muscular dystrophy (DMD) is caused by pathogenic variants in the DMD gene leading to the lack of dystrophin." (PMID 31896777, 2020). "Importantly, CD82 expression is reduced in cell lines and muscle tissue from Duchenne muscular dystrophy (DMD) patients, suggesting that its expression is affected by loss of dystrophin." (PMID 33243288, 2020). "Duchenne muscular dystrophies (DMDs) are X-linked recessive neuromuscular disorders with malfunction or absence of the Dystrophin protein." (PMID 33176713, 2020).